RN7SL869P (RNA, 7SL, cytoplasmic 869, pseudogene)
Gene: Miscellaneous RNA gene on chromosome 7 (80,245,926 to 80,246,225, forward strand). Ensembl gene ENSG00000244392.
Homologues: Orthologues: chimpanzee Metazoa_SRP (96% identical), macaque Metazoa_SRP (92% identical). Paralogues in human: RN7SL1 (79% identical), RN7SL126P (79% identical), RN7SL2 (79% identical), RN7SL3 (78% identical), RN7SL336P (78% identical), RN7SL507P (77% identical), RN7SL664P (77% identical), RN7SL296P (77% identical), RN7SL709P (77% identical), RN7SL786P (77% identical), RN7SL118P (76% identical), RN7SL220P (76% identical), and 701 more.